MMP7 (matrix metallopeptidase 7)
Diseases named in the same sentence as MMP7 in open-access papers (continued):
Sharing a sentence is not in itself a finding about the gene and the disease.
renal fibrosis (35 papers, 2013 to 2025). A final common manifestation of a wide variety of chronic kidney diseases characterized by glomerulosclerosis and tubulointerstitial fibrosis. "Conversely, Vinpo-treated rats effectively remitted these alterations, providing that Vinpo elicited suppression of EMT-associated G2/M arrest and renal fibrosis, likely through its inhibitory effect on the β-catenin/Snail1 and MMP7 pathways." (PMID 39276250, 2025). "The liberation of β-catenin caused by MMP-7-mediated degradation of E-cadherin provides a rational explanation for why MMP-7 promotes renal fibrosis." (PMID 32630493, 2020). "Some retrospective follow-up studies also show that an increase in serum MMP-7 levels is associated with a high risk of poor renal outcome and renal fibrosis." (PMID 32630493, 2020). "Recent evidence suggests that MMP-7 is not only a biomarker for renal fibrosis but also a major pathogenic mediator in fibrotic lesion progression." (PMID 28239354, 2017). "However, other studies confirmed that urine MMP7 levels were positively associated with renal fibrosis scores and negatively correlated with renal function progression." (PMID 37181812, 2023). "Furthermore, MMP1 and MMP7 are associated with the inflammatory process resulting in the development of renal fibrosis." (PMID 35045102, 2022). "MMP-7 and MMP-9 are associated with a profibrotic effect and are protective against renal fibrosis after unilateral ureteral obstruction." (PMID 39033222, 2024). "The disequilibrium between the increased expression of TIMP1 and the inhibited expression of MMP7 is likely to lead to an imbalance in the production and degradation of the extracellular matrix, which in turn promotes renal fibrosis." (PMID 37104396, 2023). "The data showed a significantly increased expression of MMP-9 and the decreased expressions of MMP-7 and MMP-13 were associated with UUO-induced renal fibrosis." (PMID 35754468, 2022). "TSN reduced renal fibrosis and improved pathological damage in the kidney in vivo through the regulation of GJA1, CTGF, MMP7, and CCL5, which are genes associated with ECM deposition." (PMID 34539795, 2021). "TGFβ induces the expression of MMP-7 which indirectly promotes renal fibrosis through EMT by damaging the epithelial integrity of the renal tubule." (PMID 35059392, 2021). "Along these lines, it appears that MMP-7 plays an important role in the onset and progression of renal fibrosis by impairing the integrity of renal tubular epithelium and causing partial EMT." (PMID 32630493, 2020). "MMP-7 also promotes renal fibrosis by proteolytically activating MMP-2 and MMP-9 from their latent zymogen forms." (PMID 32630493, 2020). "MMP-7 has been investigated in renal fibrosis in light of EMT and thought to be involved by a variety of mechanisms." (PMID 33409288, 2020). "In tissues from cats with CKD, transcript abundance of MMP2 and MMP7 was correlated with worsening degrees of renal fibrosis." (PMID 32468592, 2020). "An MMP-7-knockout mouse model showed that MMP-7 is an important pathogenic mediator that triggers the activation of β-catenin signaling and promotes renal fibrosis." (PMID 28239354, 2017). "MMP-7 is a downstream target gene of Wnt/β-catenin signaling and is involved in renal fibrosis via β-catenin signaling." (PMID 28239354, 2017). "All members of the WNT protein family (except WNT5b, WNT8b, and WNT9b), β-catenin, Dkk-1, FZD, fibronectin, and MMP-7 were upregulated in the UUO model of renal fibrosis." (PMID 24465439, 2014). "We conclude, based on the inability to detect active MMP-7 in the aging kidney, that pro-MMP-7 is upregulating collagen expression and, therefore, has a pathophysiological role in renal fibrosis." (PMID 24273653, 2013). "Also, MMP-7 have been studied in the pathogenesis of various disease processes including pulmonary and renal fibrosis, inflammatory bowel disease, and carcinogenesis." (PMID 38978022, 2024).
renal fibrosis (continued). "We found that hyperoxia exposure during nephrogenesis was associated with increased renal fibrosis markers in adulthood, including elevated TGF-β1 kidney expression, upregulation of MMP-7 and MMP-9 and downregulation of genes involved in the antifibrotic BMP signaling pathway." (PMID 39033222, 2024). "Therefore, additional studies are needed on MMP-7 to evaluate its role in renal fibrosis involvement." (PMID 37762322, 2023). "Furthermore, MMP-7 promotes the degradation of nephrin, which compromises the integrity of the slit diaphragm and ultimately leads to proteinuria and renal fibrosis." (PMID 37626956, 2023). "Therefore, further study should be performed to explore the role of MMP-7 as a therapeutic target of renal fibrosis." (PMID 34992536, 2021). "Furthermore, MMP-7, via its proteolytic activity, mediates proteolytic degradation of E-cadherin, resulting in β-catenin liberation and activation, leading to renal fibrosis in a Wnt-independent fashion." (PMID 34483931, 2021). "Moreover, knockdown of BRG1 also significantly attenuated renal expression of the key transcriptional targets of Wnt/β-catenin, including MMP-7, snail-1 and PAI-1, all of which are verified pathogenic mediators of renal fibrosis." (PMID 34318888, 2021). "Similarly to renal fibrosis, MMP-7 is able to shed E-cadherin in alveolar epithelial cells, leading to activation of β-catenin signaling and by the induction of Fas, leading to apoptosis of AECs." (PMID 33409288, 2020). "Induction of MMP-7 is a common finding in a wide variety of CKD characterized by renal fibrosis." (PMID 32630493, 2020). "MMP-7 has been more accurately described in other pathologies, such as pulmonary and renal fibrosis, which can be used to generate hypotheses about the involvement of MMP-7 in BA." (PMID 33409288, 2020). "In mice with renal fibrosis, MMP-7 was blocked by MMP inhibitor II." (PMID 33409288, 2020). "In cancer and renal fibrosis, MMP-7 is one of the downstream molecules transcribed by β-catenin." (PMID 33409288, 2020). "Furthermore, MMP-7 promotes renal fibrosis by inducing E-cadherin proteolytic degradation, ECM accumulation, and TGF-βsignaling activation." (PMID 28239354, 2017). "Moreover, elevated urinary levels of MMP-7 have been reported in patients with various kidney diseases compared to healthy controls and correlated well with renal fibrosis scores." (PMID 29123184, 2017). "Furthermore, pharmacological inhibition of MMP-7 reduced the extent of renal fibrosis markers." (PMID 33409288, 2020). "Therefore, baicalein may suppress hyperuricemia-induced renal fibrosis involving MMP-7 and MMP-9 signals." (PMID 28445133, 2017). "Despite a lot of evidence of renal fibrosis being triggered by high MMP-7 activity, some researchers found that MMP-7 is renoprotective in different AKI models." (PMID 37762322, 2023). "Wnt/β-catenin elicited renal fibrosis by inducing multiple fibrogenic genes such as RAS components, matrix metalloproteinase-7 (MMP-7), plasminogen activator inhibitor 1 (PAI-1), and Snail1." (PMID 35227255, 2022). "In the UUO and I/R models, SIRT1 activation improved renal fibrosis in proximal tubular cells by deacetylating SMAD3 and SMAD4 and blocking the effect of TGF-β signaling on matrix metalloproteinase-7 (MMP-7), which normally cleaves E-cadherin." (PMID 35277012, 2022). "Induced matrix metalloproteinase-7 (MMP-7) can then activate MMP-2 and MMP-9 by proteolysis, thus leading to renal fibrosis by degrading collagen IV and promoting EMT." (PMID 35059392, 2021). "The downstream target genes of the Wnt canonical pathway are all involved in renal fibrosis, including fibronectin 1 (FN1), Cluster of differentiation 44 (Cd44), fibroblast specific protein-1 (FSP-1), and matrix metalloproteinase-7 (MMP-7)." (PMID 35059392, 2021). "In human beings, MMP‐7 is recognized as both an important mediator of fibrosis in CKD, as well as a urinary biomarker of renal fibrosis." (PMID 32468592, 2020).
renal fibrosis (continued). "MMP7, a member of the MMP family, can cleave a series of matrix and protein fragments, and release growth factors from the extracellular matrix, while promoting renal fibrosis." (PMID 34539795, 2021). "Interestingly, some studies have reported the importance of MMP7 in CKD, highlighting this protease as a key regulator of renal fibrosis through three main pathways, transforming growth factor-beta (TGF-β) signalling, epithelial-mesenchymal transition (EMT) and ECM deposition." (PMID 35045102, 2022). "Furthermore, it was verified that TSN could regulate the levels of GJA1, CTGF, MMP7, and CCL5 and alleviate renal fibrosis in DN." (PMID 34539795, 2021). "SIRT1 up-regulation by resveratrol treatment ameliorated renal fibrosis in proximal tubular cells treated with TGF-β in addition to a mouse model of UUO; this was found to be due to inhibition of the EMT through deacetylation of Smad4 and inhibition of matrix metalloproteinase-7 (MMP-7)." (PMID 32932720, 2020). "Although EMT may not be the mechanism by which renal fibrosis occurs, MMP-7 is thought to be actively involved in the mechanism of renal fibrosis because the extent of renal fibrosis was markedly reduced in MMP-7 gene knockout mice compared with wildtype mice." (PMID 33409288, 2020).
liver fibrosis (23 papers, 2012 to 2026). "Higher serum MMP-7 levels were found to be associated with more severe liver damage and biliary injury, and a higher incidence of liver fibrosis, and perforation." (PMID 38914992, 2024). "Our results have identified heat shock proteins, phosphorylation-associated enzymes, or kinases, such as Sm16, GSTA3, GPCRs, EF1-α, MMP7, and other proteins linked to schistosome-induced liver fibrosis." (PMID 36986363, 2023). "Due to pronounced age-related heterogeneity in BA presentations (e.g., variable hepatic fibrosis severity in neonates vs infants), stratified analyses of MMP-7 diagnostic thresholds and performance across age brackets (0–2 weeks, 2–4 weeks, 1–3 months, >3 months) are strongly recommended." (PMID 40642008, 2025). "Notably, MMP-7 expression levels correlate significantly with BA-associated liver fibrosis, further underscoring its biomarker potential." (PMID 40642008, 2025). "Hepatic fibrosis occurs earlier and faster in infants with BA than other causes of cholestasis and MMP7 is involved in the development of liver fibrosis, therefore inhibitors of this factor may be useful in preventing liver fibrosis." (PMID 35717157, 2022). "Moreover, LSM’s positive predictive value is relatively modest; which suggests the strength of the association between MMP7 and liver fibrosis may be conservative." (PMID 33536476, 2021). "Serum and liver tissue samples from BA patients were collected to analyze the correlation between MMP7 and liver fibrosis." (PMID 41828435, 2026). "MMP-7 regulated collagen-I expression through Wnt/β-catenin or MAPK signaling in liver fibrosis and kidney fibrosis." (PMID 40722657, 2025). "Previous studies reported that β-catenin/MMP-7 regulated collagen-I expression via the EMT process in liver fibrosis." (PMID 40722657, 2025). "Our study demonstrated that MFAP4 outperformed MMP7 in accurately assessing the severity of liver fibrosis in patients with BA." (PMID 40492258, 2025). "We evaluated the relationships between serum MMP-7 and age, laboratory tests, imaging examinations, liver fibrosis, MMP-7 expression, and perforation." (PMID 38914992, 2024). "We also observed significant correlations among MMP-7 levels, liver fibrosis, the results of specific liver tests and bile acid levels, shedding light on their potential roles in assessing disease severity." (PMID 38141111, 2024). "Higher serum MMP-7 was correlated with younger age at diagnosis (p < 0.001), larger cyst sizes (p < 0.001), higher liver fibrosis stages (p < 0.001), and higher incidence of perforation (p < 0.01)." (PMID 38914992, 2024). "Our results indicated a significant positive correlation between the liver fibrosis score and MMP-7 expression levels (P < 0.05), with a correlation coefficient of 0.57." (PMID 38141111, 2024). "In this study, we found that MMP-7 levels were highly correlated with liver fibrosis, which is consistent with most studies." (PMID 38141111, 2024). "Patients with high serum MMP-7 were more likely to have severe liver damage and biliary injury, with higher incidences of liver fibrosis and perforation." (PMID 38914992, 2024). "Fourth, our study not only focused on BA diagnosis but also explored the correlation among MMP-7 levels, liver test results, bile acid levels, and liver fibrosis." (PMID 38141111, 2024). "Currently, our findings have identified the heat shock protein, phosphorylation-associated enzymes or kinases, Sm16, GSTA3, MMP7, GPCRs, EF1-α, and other protein components that have been associated with schistosome-induced liver fibrosis." (PMID 36986363, 2023). "Suggested that MMP-7 was produced by severe bile duct inflammation and promoted liver fibrosis through the E-cadherin/β- catenin pathway." (PMID 35717157, 2022). "The diagnostic performance of serum MMP-7 in the early diagnosis of BA and its good level of evidence for predicting post-KPE significant liver fibrosis are presented here." (PMID 34083585, 2021).
liver fibrosis (continued). "Exploring and establishing the exact role that MMP-7 has in BA can provide new therapeutic targets that can be explored in order to prevent liver fibrosis or even prevent BA from occurring." (PMID 33409288, 2020). "MMP-7 can be involved during the initiation of cholangiocyte damage leading to BA as well as during the progression of liver fibrosis that is observed in these patients." (PMID 33409288, 2020). "Hepatic expression of MMP-7 correlated with the extent of liver fibrosis in two cholestatic patient cohorts." (PMID 33409288, 2020). "Multiple studies have shown that serum MMP-7 measurements are able to accurately diagnose BA in a cohort of cholestatic patients while hepatic MMP-7 expression correlated with BA-related liver fibrosis." (PMID 33409288, 2020). "In BA, hepatic MMP-7 expression correlates with the extent of liver fibrosis, even with minimal cholestasis after the performance of a KPE." (PMID 33409288, 2020). "A recent trial, however, found that serum MMP-7 was a reliable biomarker of advanced liver fibrosis and cirrhosis." (PMID 33409288, 2020). "In contrast to previous studies, hepatic expression of MMP-7 correlated to the Metavir liver fibrosis stage despite a successful KPE indicating that hepatic overexpression of MMP-7 can occur independent of cholestasis." (PMID 33409288, 2020). "The most significant and novel biomarker for advanced liver fibrosis we discovered was MMP7, which had a similar odds ratio to HA for the prediction of significant or advanced fibrosis." (PMID 27861569, 2016). "Results showed that MMP7 was positively correlated with liver fibrosis in BA patients." (PMID 41828435, 2026). "MMP7, a frequently employed biomarker in BA, despite significant variations in threshold levels among studies due to different measurement methods, is intimately correlated with the degree of liver fibrosis." (PMID 40492258, 2025). "Therefore, prenatally diagnosed patients were more likely to experience liver fibrosis and perforation and had higher levels of serum MMP-7 than postnatally diagnosed patients in our study, which further emphasized the importance of prompt surgery." (PMID 38914992, 2024). "In addition, we found that MMP-7 levels were highly correlated with gamma-glutamyl transferase levels and the liver fibrosis score." (PMID 38141111, 2024). "However, most studies have reported that MMP-7 levels are positively correlated with liver fibrosis." (PMID 38141111, 2024). "It was noticed that MMP-7 levels were higher in BA patients especially those with higher stages of liver fibrosis, indicating MMP-7 might be involved in the pathogenesis and progression of BA." (PMID 38978022, 2024). "Our study confirmed a positive correlation between serum MMP-7 and liver fibrosis stages, which might have resulted from biliary obstruction as reported." (PMID 38914992, 2024). "Patients with other hepatobiliary diseases can also have liver fibrosis and elevated MMP-7 levels, however, around the cutoff value, indicating that the regulatory pathways of MMP-7 in non-BA may be different from those associated with BA." (PMID 38978022, 2024). "In our patient cohort, the association between MMP7 and liver fibrosis was independent of T2D and impaired renal function (assessed by eGFR), common comorbidities in patients with NAFLD." (PMID 33536476, 2021). "Regarding the prediction of post-KPE prognosis, a higher serum IL-18 level indicates the occurrence of persistent jaundice; an increased value of APRi, preoperative serum MMP-7 level or postoperative serum HA level predicts the occurrence of significant liver fibrosis." (PMID 34083585, 2021). "It is tempting to speculate that OPN and MMP-7 may be engaged in a positive feedback loop in BA, leading to the progressive liver fibrosis that is observed in a similar manner as in IPF." (PMID 33409288, 2020).